EIF3D (eukaryotic translation initiation factor 3 subunit D)
Diseases named in the same sentence as EIF3D in open-access papers (continued):
Sharing a sentence is not in itself a finding about the gene and the disease.
cervical cancer (4 papers, 2022 to 2024). A primary or metastatic malignant neoplasm involving the cervix. "Studies in cervical cancer have also shown that eukaryotic initiation factor (EIF3D) promotes the development of cervical cancer by activating the GRP78/FAK signaling pathway." (PMID 37858217, 2023). "In this study, we also revealed that EIF3D promoted stem cell-like properties and metastasis of cervix cancer cells via targeting GRP78-FAK axis." (PMID 35104170, 2022). "We then detected the expression of EIF3D in cervix cancer cell lines including HeLa, CaSKi, and SiHa, and normal cervix cell line H8." (PMID 35104170, 2022). "We further found the downregulation of EIF3D suppressed the proliferation, motility, and the stem cell-like properties of cervix cancer cells." (PMID 35104170, 2022). "Through qPCR assays, we found the high mRNA levels of EIF3D in cervix cancer tissues, compared with normal tissues." (PMID 35104170, 2022). "We found that EIF3D was highly expressed in cervix cancer cells, and knockdown of EIF3D inhibited the proliferation, migration, and stem cell-like properties of cervix cancer cells." (PMID 35104170, 2022). "EIF3D plays a role in the progression and development of multiple tumors, but its possible role in cervix cancer progression is still unclear." (PMID 35104170, 2022). "Mechanically, we found EIF3D promoted FAK activation through GRP78 in cervix cancer cells, therefore contributing to the progression of cervix cancer." (PMID 35104170, 2022). "The expression of EIF3D was altered in cervix cancer cells, HeLa cells, by the transfection of EIF3D overexpression plasmids and shRNA plasmids." (PMID 35104170, 2022). "To uncover the possible effects of EIF3D on cervix cancer, we first detected its expression levels in human cervix cancer tissues and normal tissues." (PMID 35104170, 2022). "Through qPCR assays, we noticed that the mRNA level of EIF3D was upregulated in these three types of cervix cancer cell lines." (PMID 35104170, 2022). "Further through MSFE and immunoblot assays, we found that EIF3D promoted the stem cell-like properties of cervix cancer cells." (PMID 35104170, 2022). "Further mechanistic studies confirmed that EIF3D promoted FAK activation through GRP78 in cervix cancer cells, thereby promoting cervix cancer progression." (PMID 35104170, 2022). "MTT assays results indicated that EIF3D overexpression significantly promoted the viability of cervix cancer cells, whereas its downregulation suppressed the cell viability." (PMID 35104170, 2022). "We further found that downregulation of EIF3D suppressed the proliferation and motility of cervix cancer cells." (PMID 35104170, 2022). "Subsequently, we detected the effects of EIF3D on the migration and invasion of cervix cancer cells through transwell assays." (PMID 35104170, 2022). "In vitro and in vivo model studies have shown that GRP78, a multifunctional calcium-binding ER protein, interacts with EIF3D to inhibit GRP78, and reducing EIF3D influence on the Warburg effect (i.e., aerobic glycolysis) and cell growth in an in vitro cervical cancer model." (PMID 38711526, 2024). "EIF3D ablation restrained the stem cell-like properties in cervix cancer cells." (PMID 35104170, 2022). "We should next detect the effects of EIF3D on the cell cycle of cervix cancer." (PMID 35104170, 2022). "EIF3D depletion suppressed tumor growth of cervix cancer cells via GRP78-FAK axis." (PMID 35104170, 2022). "Since previous study indicated that EIF3D could interact with GRP78, which was a CSC marker, we next detected the effects of EIF3D on the stem cell-like properties of cervix cancer cells." (PMID 35104170, 2022). "Therefore, downregulation of EIF3D suppressed tumor growth of cervix cancer cells via GRP78-FAK axis." (PMID 35104170, 2022). "Interestingly, we found here a member of eukaryotic translation initiation factor 3 (EIF3), EIF3D, had the potential to serve as a target of cervix cancer via mediating stem cell-like properties." (PMID 35104170, 2022).
cervical cancer (continued). "In this study, we investigated the role of EIF3D in cervix cancer." (PMID 35104170, 2022). "EIF3D promoted FAK activation through GRP78 in cervix cancer cells." (PMID 35104170, 2022). "Collectively, downregulation of EIF3D restrained the motility of cervix cancer cells." (PMID 35104170, 2022). "Knockdown of EIF3D restrained the motility of cervix cancer cells." (PMID 35104170, 2022). "EIF3D depletion suppressed the proliferation of cervix cancer cells." (PMID 35104170, 2022). "In this study, we found the high EIF3D expression in human cervix cancer tissues." (PMID 35104170, 2022). "EIF3D had high expression in human cervix cancer tissues and cells." (PMID 35104170, 2022). "Similarly, the immunoblot assays also revealed the high EIF3D protein levels in cervix cancer cell lines." (PMID 35104170, 2022). "In conclusion, we noticed the high EIF3D expression in human cervix cancer tissues and cells." (PMID 35104170, 2022). "Therefore, our data demonstrated the involvement of EIF3D in the progression of cervix cancer." (PMID 35104170, 2022). "Similarly, in cervix cancer, we also found that EIF3D could mediate the expression of GRP78, thereby promoting stem cell-like properties and metastasis." (PMID 35104170, 2022). "Therefore, we detected the effects of EIF3D on FAK phosphorylation levels in cervix cancer cells." (PMID 35104170, 2022). "Therefore, we speculated that EIF3D might affect the stem cell-like properties of cervix cancer cells through GRP78." (PMID 35104170, 2022). "Our results suggest that EIF3D could be a potential therapeutic target for cervix cancer." (PMID 35104170, 2022). "Interestingly, we also noticed here that EIF3D could promote the stem cell-like properties of cervix cancer via GRP78." (PMID 35104170, 2022). "Therefore our results suggested that EIF3D could serve as a promising target of cervix cancer." (PMID 35104170, 2022). "Mechanically, we found that EIF3D promoted FAK activation through GRP78 in cervix cancer cells, thus contributing to the progression of cervix cancer." (PMID 35104170, 2022). "Studies have shown that high expression of the EIF3D gene promotes cell growth and the Warburg effect in cervical cancer models in vitro, while inhibition of GRP78 reduces the influence of EIF3D on the Warburg effect of cervical cancer in vitro." (PMID 37858217, 2023). "Through IHC assays, we further confirmed the high EIF3D expression in human cervix cancer tissues compared with normal tissues." (PMID 35104170, 2022).
lung carcinoma (4 papers, 2022 to 2025). "This interaction leads to the regulation of SLC7A11 expression by RBMS1 through EIF3D, consequently inhibiting ferroptosis and promoting the progression of lung cancer." (PMID 38654320, 2024). "Another study indicated that the depletion of EIF3D restrained cell proliferation through the regulation of cell cycle in lung cancer." (PMID 35104170, 2022). "In addition, elevated RBMS1 was observed in lung cancer patients, and RBMS1 deficiency inhibited the translation of SLC7A11 and promoted ferroptosis through the translation initiation factor eIF3d." (PMID 41214391, 2025). "Several studies have already reported the harmful effect of high expression of EIF3 subunits in lung cancer, including EIF3C, EIF3D, and EIF3H." (PMID 36051357, 2022).
ovarian carcinoma (4 papers, 2016 to 2021). A malignant neoplasm originating from the surface ovarian epithelium. "Thus, we conclude that deregulation of EIF3D is associated with the occurrence and development of ovarian cancer, and our results provide the first evidence that lentivirus‐mediated knockdown of EIF3D inhibits the proliferation of ovarian tumour cell lines by inducing G2/M cell cycle arrest." (PMID 28203520, 2016). "In this study, EIF3D was overexpressed in ovarian cancer clinical tissues compared with benign ovarian cystadenoma and borderline cystadenoma." (PMID 28203520, 2016). "To determine the function of EIF3D in ovarian cancer in vitro, we knocked down the gene using lentivirus‐mediated RNAi in the ovarian cancer cell lines CAOV‐3 and SKOV‐3." (PMID 28203520, 2016). "The results presented here demonstrate that EIF3D may play an important role in the occurrence and development of ovarian cancer." (PMID 28203520, 2016). "In conclusion, EIF3D was knocked down by Lv‐shRNA in ovarian cancer cells." (PMID 28203520, 2016). "Furthermore, EIF3D expression was associated with the FIGO stage and pathological differentiation stage, which suggested that EIF3D expression correlates with the occurrence and development of ovarian cancer." (PMID 28203520, 2016). "Here, we report that eukaryotic translation initiation factor 3 subunit D (EIF3D), a member of the EIF3 family, was overexpressed in ovarian cancer clinical tissues." (PMID 28203520, 2016). "In benign ovarian cystadenoma, EIF3D expression was extremely weak or even negative, whereas it began to increase in borderline cystadenoma but remained weak compared with the ovarian cancers (P < 0.01)." (PMID 28203520, 2016). "However, the mechanisms by which EIF3D promotes oncogenesis remain unclear, and the effects of EIF3D in ovarian cancer have not been reported." (PMID 28203520, 2016).
colorectal cancer (3 papers, 2014 to 2025). A primary or metastatic malignant neoplasm that affects the colon or rectum. "In the case of EIF3D, previous research has shown that mutations in this gene play a crucial role in the progression of colorectal cancer." (PMID 40018039, 2025). "eIF3D, which is of our interest, has been reported to mutate at two points in human colorectal cancer identified by mutation spectrum." (PMID 25370813, 2014). "Recently, eIF3D was found to embed somatic mutations in human colorectal cancers, indicating its importance for tumour progression." (PMID 25370813, 2014). "Recently, mutation spectrum in human colorectal cancers revealed two point mutations of eIF3D in coding region, which might disrupt translation initiation, leading to tumourigenesis." (PMID 25370813, 2014). "Two point mutations of eIF3D were reported by mutation spectrum in human colorectal cancers." (PMID 25370813, 2014). "However, the functional role of eIF3D in colorectal cancer remains unclear." (PMID 25370813, 2014).
lymph node metastasis (2 papers, 2017 to 2022). "The clinicopathologic association study in GBCs revealed that overexpression of eIF3d was associated significantly with lymph node metastasis and liver metastasis." (PMID 28594409, 2017).
malignant mesothelioma (2 papers, 2014 to 2022). A malignant neoplasm of the pleura or peritoneum, arising from mesothelial cells. "Our data were supported by a recent study showing that knockdown of eIF3D suppressed mesothelioma cell proliferation and increased apoptosis, identifying eIF3D as a potential drug target in malignant mesothelioma." (PMID 25370813, 2014).
viral infection (2 papers, 2023). "Accumulating evidence indicates that eIF3d dysregulation contributes to tumorigenesis, cancer drug resistance, pre-eclampsia, and viral infection." (PMID 36997088, 2023). "Although greater understanding of the mechanisms of eIF3d function in viral infection and in immunity is needed, eIF3d may be a potential prognosis marker and therapeutic target for AIDS patient." (PMID 36997088, 2023).
(HCMV) infection (1 paper, 2023). "In a recent study, it was found that the eIF3d protein level increased in response to human cytomegalovirus (HCMV) infection, whereas its mRNA level remained unchanged." (PMID 36997088, 2023). "Moreover, the increased eIF3d expression during HCMV infection remodeled the global host mRNA translational landscape and switched the cap-dependent translation from an eIF4F- to an eIF3d-dependent mechanism to support productive viral replication." (PMID 36997088, 2023). "These important findings suggest that eIF3d could be developed as a target to inhibit HCMV infection." (PMID 36997088, 2023).
Anxiety (1 paper, 2025). Intense feelings of nervousness, tension, or panic often arise in response to interpersonal stresses. "In PAH rats, anxiety- and depression-like behaviors were observed, and qPCR confirmed altered expression of CHD8, DDX42, and EIF3D consistent with in-silico findings." (PMID 41280439, 2025).
astrocytoma (1 paper, 2021). "Besides the already known eIFs, we demonstrated significantly elevated protein levels of eIF3D, eIF3H, eIF3I, eIF3M, p-eIF4G, eIF4H, eIF5 and eIF6 in astrocytoma tissue compared to CCBT." (PMID 33807050, 2021).
Cholecystitis (1 paper, 2017). The presence of inflammatory changes in the gallbladder. "The expression of eIF3d levels was increased significantly in 92 human tumor samples as compared with the 103 cholecystitis gallbladder epithelial tissues." (PMID 28594409, 2017). "Herein, we for the first time demonstrate that eIF3d is involved in GBC, and this gene is highly expressed in GBCs as compared with the cholecystitis gallbladder epithelial tissues and gallbladder normal tissue adjacent tumor." (PMID 28594409, 2017).
clear cell carcinoma (1 paper, 2016). "The immunohistochemical analysis detected EIF3D expression in the ovarian adenoma, borderline lesion and cancer (serous cystadenocarcinoma, clear cell carcinoma and endometrial adenocarcinoma) tissues." (PMID 28203520, 2016).
depression (1 paper, 2025). "Candidate biomarkers including CHD8, DDX42, and EIF3D should be assessed in larger, independent cohorts of patients with PAH, with and without depression, as well as in MDD cohorts, to determine their diagnostic or prognostic potential." (PMID 41280439, 2025).
gallbladder tumor (1 paper, 2017). "To verify the positive role of eIF3d in gallbladder tumor progression in vivo, we performed xenograft tumor assays using eIF3d knockdown stable NOZ cells." (PMID 28594409, 2017). "Taken together, these data suggest that eIF3d promotes gallbladder tumor growth and migration at least partially through regulating GRK2 activity, which in turn leads to activation of PI3K/AKT signaling pathways." (PMID 28594409, 2017). "Collectively, these data support our hypothesis that eIF3d acted as a novel tumor-promoting molecule and positively regulates gallbladder tumor growth." (PMID 28594409, 2017).
head and neck squamous cell carcinoma (1 paper, 2024). A squamous cell carcinoma that arises from any of the following anatomic sites: lip and oral cavity, nasal cavity, paranasal sinuses, pharynx, larynx, and salivary glands. "Our findings suggest that EIF3D may impact the heterogeneity of the TME by modulating IGAS events, consequently influencing the progression of Head and Neck Squamous Cell Carcinoma (HNSC) and its responsiveness to immunotherapy." (PMID 38535990, 2024).
metastasis (1 paper, 2017). The spread or migration of cancer cells from one part of the body (where they first appeared) to another. "A clinicopathologic association study in GBCs demonstrated that overexpression of eIF3d was significantly associated with advanced clinical stage, and lymph node and liver metastasis." (PMID 28594409, 2017). "In order to assess the contribution of eIF3d to tumor metastasis in vivo, we used the animal model of experimental liver metastasis and pulmonary metastasis." (PMID 28594409, 2017).
nasopharyngeal carcinoma (1 paper, 2024). A carcinoma arising from the nasopharyngeal epithelium. "Polysome profiling assays further demonstrated that overexpressing or knocking down EIF3D in nasopharyngeal carcinoma cells could partially counteract circCDYL2’s influence on RAD51 translation." (PMID 38654320, 2024). "Further investigation revealed that circCDYL2 recruits EIF3D to promote RAD51 translation initiation, thereby fostering homologous recombination repair and contributing to radiation resistance in nasopharyngeal carcinoma." (PMID 38654320, 2024). "Following the overexpression or knockdown of circCDYL2 in nasopharyngeal carcinoma cells, RIP experiments revealed that the binding of EIF3D protein to RAD51 mRNA increased or decreased correspondingly." (PMID 38654320, 2024).
ovarian tumour (1 paper, 2016). "3‐(4,5‐dimethylthylthiazol‐2‐yl)‐2 (MTT) and colony formation assays revealed that the lentivirus‐mediated knockdown of EIF3D suppresses cell proliferation in the ovarian tumour cell lines CAOV‐3 and SKOV‐3." (PMID 28203520, 2016).
renal carcinoma (1 paper, 2023). A carcinoma arising from the epithelium of the renal parenchyma or the renal pelvis. "Interestingly, EIF3D overexpression is a driver of sunitinib resistance in renal cancer and another study has shown that SETD2 mutations are associated with sunitinib resistance." (PMID 37528416, 2023).